MPC1 (mitochondrial pyruvate carrier 1)
Diseases named in the same sentence as MPC1 in open-access papers (continued):
Sharing a sentence is not in itself a finding about the gene and the disease.
tumor (continued). "MPC1 overexpression in renal cell carcinoma inhibited tumor growth and invasion in vivo." (PMID 36902385, 2023). "The role of glycolytic pathways in tumor progression can be weakened by inhibiting the pyruvate to lactic acid conversion but transferring this metabolite to mitochondria through mitochondrial pyruvate complex (MPC) composed of two complexes: MPC1 and MPC2." (PMID 36213830, 2022). "Interestingly, Mpc1 levels were elevated in Tpex, a TIL subset essential for maintaining antitumor function and for response to immune checkpoint blockade, and MPC1 deletion significantly reduced their numbers in the tumor." (PMID 35452600, 2022). "Mitochondrial pyruvate complex (MPC) comprised of pyruvate carriers 1 and 2 (MPC1/MPC2) is the entry point for pyruvate to the mitochondrial matrix for oxidative metabolism, and MPC deficiency contributes to tumor initiation and progression by enhancing glycolysis." (PMID 34980012, 2022). "Taken together, these findings indicate that MPC1 is involved in various tumour progression processes and might be a promising target for cancer treatment." (PMID 34059057, 2021). "It has been reported that the effects of glycolysis on tumor progression can be diminished by diverting the metabolite pyruvate from conversion to lactate in part through transport into the mitochondria via the activity of the MPC1/MPC2 heterodimer." (PMID 34030708, 2021). "Collectively, these data suggested that MPC1 maybe serves as a suppressor to disrupt tumor malignancy." (PMID 32851100, 2020). "Inspired by this, we assumed that MPC1 could mediate tumor cell motility through affecting MMP7 activity, cell-cell contacts, and EMT." (PMID 32851100, 2020). "These phenomena together with our results indicate that MPC1 could act as a tumor suppressor through inhibiting tumor metastasis." (PMID 32851100, 2020). "As expected, COUP-TFII knockdown induced the expression of MPC1 in tumor samples." (PMID 26895100, 2016). "Interestingly, we demonstrated that DHEA educated TAMs in a less aggressive phenotype, reducing the gene expression of several markers of TAM phenotype, including IL-6, MMP-9, VEGF, IL-10, and MPC-1, which sustain tumor invasiveness, angiogenesis, and metastasis." (PMID 36765778, 2023). "Considering the detrimental effects of MPC1 deletion on T cell function in a tumor microenvironment, we wondered if we could harness the use of an MPCi for imprinting a memory fate in in vitro, expanding T cells for ACT immunotherapy without permanently abrogating MPC activity." (PMID 35452600, 2022). "However, the specific role of MPC1 on tumor metastasis in CRC remains unexplored." (PMID 32851100, 2020). "Finally, we carried out an ex vivo assay to ask whether COUP-TFII regulates tumor growth in vivo in a MPC1 dependent manner." (PMID 26895100, 2016). "In tumor cells, YBX1 localizes to the mitochondrial intermembrane space and binds to MPC1/2, thereby inhibiting mitochondrial pyruvate uptake." (PMID 40812419, 2025). "Our findings point to distinct metabolic profiles in PDAC subtypes with basal-like tumor PDOs showing higher OXPHOS and sensitivity to MPC1 inhibition." (PMID 39363341, 2024). "The expression of the three genes, COQ2, MPC1, and ADAMTS13, in normal and tumor tissues was analyzed, revealing that the expression of MPC1 was higher in normal tissues, while ADAMTS13 was higher in tumor tissues." (PMID 37691826, 2023). "It was observed that the expression level of MPC1 was clearly elevated in adjacent normal tissues comparing with CRC, while ADAMTS13 was considerably upregulated in tumor tissues in contrast to normal tissues." (PMID 37691826, 2023). "Cui and colleagues noted a significant reduction in MPC1 expression (both at the mRNA and protein levels) in PDAC cell lines and tumour tissues compared to adjacent non-tumour controls." (PMID 36672360, 2023).
tumor (continued). "The mitochondrial pyruvate carrier (MPC) complex, which consists of MPC1 and MPC2, is required for efficient glucose production, and decreased MPC activity in tumors enhances glycolytic activity, resulting in tumor progression." (PMID 34980012, 2022). "MPC complex regulated mitochondrial pyruvate flow inhibited the MPC1 and MPC2 expression in cancer cells and promoted glycolysis and lactate synthesis in tumor samples." (PMID 36213830, 2022). "Using a single-cell tumor-infiltrating lymphocyte (TIL) reference atlas, we observed that Mpc1 was significantly more expressed in progenitor exhausted (Tpex) than in terminally exhausted (Tex) TILs, whereas Mpc2 levels remained unaltered." (PMID 35452600, 2022). "Mitochondrial Pyruvate Carrier 1 (MPC1), one of the rate-limiting proteins involved in glycolysis metabolism, has been demonstrated as a tumor inhibitor in several cancers." (PMID 33791391, 2021). "It was found that MPC1 was downregulated in CRC and its low expression was correlated with poor prognosis; Mechanically, decreased MPC1 enhanced tumor metastasis by activating the Wnt/β-catenin pathway." (PMID 34035992, 2021). "We found that knockdown of PDHA1 and MPC1 reversed the avidity of PGC1α overexpression cells for OXPHOS and blocked tumor cells migration and invasion mediated by PGC1α." (PMID 29700317, 2018). "Cytoplasmic MPC1 and MPC2 proteins were highly expressed in 10 normal esophageal epithelia adjacent to tumor." (PMID 27911865, 2017). "We hypothesized that the MPC1 KO mice were able to utilize more glucose for energy production than the WT mice, since the increased glycolysis in the mitochondrial function depressed tumour cells usually leads to reduced ATP production as known as Warburg effect." (PMID 27835892, 2016). "With this assay, we showed that COUP-TFII knockdown inhibited tumor growth and tumor burden, and this inhibition was abolished when MPC1 expression was repressed, suggesting that MPC1 is critical for COUP-TFII regulated tumor growth." (PMID 26895100, 2016). "To investigate whether MPC1 inhibition increases glycolysis or reduces OXPHOS in tumor cells, we measured ECAR and OCR in PDOs treated with the MPC1 small molecule inhibitor UK-5099." (PMID 39363341, 2024). "The expressions of MPC1 and MPC2 were then determined in 30 paired tumor and adjacent non-tumor tissues of OC using qRT-PCR analysis, as well as in another 205 paired tumor and adjacent non-tumor tissues of OC using IHC analysis." (PMID 38615083, 2024). "Accordingly, MPC1 KO CD8+ T cells in the tumor were phenotypically not more terminally exhausted, but their progenitor exhausted population was significantly reduced." (PMID 35452600, 2022). "Surprisingly, however, MPC1 KO ACT was not able to control tumor growth as compared with untreated mice, whereas WT ACT did." (PMID 35452600, 2022). "Intriguingly, silencing of MPC1 diminishes the effect of COUP-TFII on glycolysis in vitro and tumor growth in vivo, suggesting other metabolites may compensate for the TCA cycle intermediates (such as glutamine) under MPC1 knockdown conditions." (PMID 34948229, 2021). "MPC1 is significantly depressed in CRC, both in human tumour tissues and in mouse models." (PMID 34059057, 2021). "The results indicated that MPC1 expression was significantly decreased in tumour tissues compared to that in non-cancerous tissues." (PMID 34059057, 2021). "To determine the status of MPC1 in LAC, we examined the expression of MPC1 in nine pairs of LAC tissues, and found that MPC1 was lowly expressed in LAC tissues as compared with corresponding adjacent non-tumor tissues." (PMID 30770798, 2019). "The expression of MPC1 was negatively correlated with the MYC oncogene and positively correlated with the colon tumor suppressor APC also supported this hypothesis." (PMID 27911865, 2017).
tumor (continued). "Further analysis of the tumor samples for cell proliferation indicated that knockdown of COUP-TFII reduced cell proliferation as indicated by Ki67 positive cells, and this reduction was abolished by simultaneous repression of MPC1 expression." (PMID 26895100, 2016). "Kaplan-Meier survival curves and the log-rank test demonstrated that patients with positive expression of MPC1 in the tumor had significantly better OS than the patients with negative MPC1 expression in the tumor (P =0.007)." (PMID 27852261, 2016). "As expected, WT tumor-infiltrating CD8+ T cells showed a significant suppression of cytokine production and cytotoxic degranulation as compared with those residing in the spleen, however, MPC1 KO T cells displayed a total collapse of their effector function when entering the tumor." (PMID 35452600, 2022). "The severe impairment in effector function of MPC1 KO T cells specifically in the tumor, but not in the spleen, might be explained by the difference in metabolite abundance between those tissues." (PMID 35452600, 2022). "However, the relationship between the metabolism and tumor metastasis regulated by MPC1 was not being mentioned." (PMID 32851100, 2020). "Interestingly, in the course of data analysis, we found that the expression of MPC1 was decreased at the stage of intestinal inflammation, which was not different from that in tumor tissue." (PMID 32851100, 2020). "Additionally MPC1 was negatively correlated with tumor size and TNM stages, but not related with tumor location, histological grade, EGFR mutation." (PMID 30770798, 2019). "Moreover, it has shown in some studies that the expression levels of MPC1 and MPC2 in cancers are decreased, and low expression is correlated with poor survival in multiple cancers, including colon, kidney and lung, illustrating the regulation of MPC complex is pivotal for tumor cell growth." (PMID 27852261, 2016). "Real-time quantitative PCR results disclosed that MPC1, ZG16, RBM47, CPM and DNASE1L3 were expressed at higher levels in adjacent normal tissues than in tumor tissues, and SMOX expression was higher in tumor tissues than in non-tumor tissues." (PMID 38914961, 2024). "Low or absent MPC1 and MPC2 levels lead to metabolic disorders and alterations in tumor metabolism, and their restored expression inhibits tumor growth, invasiveness, metastasis, and stemness." (PMID 38926418, 2024).
cancer (44 papers, 2015 to 2025). A tumor composed of atypical neoplastic, often pleomorphic cells that invade other tissues. "MPC1 is downregulated in several cancers and in the glycolytic PDAC subtype associated with poor prognosis." (PMID 39363341, 2024). "MPC1 deficiency was recently found to be strongly associated with various diseases and cancer hallmarks." (PMID 34059057, 2021). "As shown in the literature, MPC1 expression is significantly decreased in cancer tissue and associated with poor prognosis." (PMID 34059057, 2021). "Specifically, B cell, CD8+ T cell, dendritic cell (DC), macrophage, and neutrophil infiltration showed a significant association with MPC1 expression across cancers." (PMID 34059057, 2021). "Downregulation of MPC1 is associated with poor cancer prognosis, and MPC1 is particularly interesting as a potential therapeutic target." (PMID 34059057, 2021). "Decreased MPC1 expression facilitates a reduction in the conversion of pyruvate into circulating lactate and plays an important role in regulating cancer-associated metabolism." (PMID 34059057, 2021). "The results of this research indicate that the deficiency of MPC1 influences the expression of various genes that are involved in in the metabolism of cancer." (PMID 30397542, 2018). "Our current study has demonstrated that MPC1 deletion in cancer cells caused a reduced cell growth and slow cell cycling in MPC1−/− cells." (PMID 28624784, 2017). "Positive MPC1 or MPC2 expression in cancer tissues was significantly associated with higher OS (P < 0.05)." (PMID 27852261, 2016). "In addition, MPC1 deficiency significantly increased cancer stem cell markers such as Nanog homeobox (NANOG), octamer-binding transcription factor 4 (OCT4), and SRY-box transcription factor 2 (SOX2) in LUAD cells in vivo." (PMID 34059057, 2021). "Aberrant expression of MPC1 is also involved in cancer-associated metabolic dysregulation." (PMID 34059057, 2021). "Conclusively, these data indicate MPC1 deficiency increased cancer stem-like traits of LAC cells." (PMID 30770798, 2019). "MPC1 is often lost in cancer cells, and its expression is linked with anti‐proliferative phenotype." (PMID 28369883, 2017). "For MPC1, the middle section was the predominant location for cancer cells, whereas the upper part also contributed significantly to MPC2 and MPC3 expression." (PMID 38486026, 2024). "During recent years, studies have reported that the expression of MPC1 was decreased in several types of human cancers, which result in suppression of MPC activity and cancer progression." (PMID 38615083, 2024). "In line with previous reports on other cancer types, this study revealed that in BCa, MPC1 was frequently deleted, while MPC2 was mostly amplified." (PMID 34980012, 2022). "Based on an analysis of public data, the MPC1 mRNA expression level is a potential prognostic indicator of cancer." (PMID 34059057, 2021). "The downregulation of MPC1 and MPC2 has been associated with a pro-tumorigenic phenotype and in many cancers a poor clinical outcome." (PMID 33804985, 2021). "Because our aim was to determine the expression patterns and prognostic value of MPC1 across cancers, we analysed the expression status of MPC1 at the mRNA level and then explored its relationship with prognosis across cancers using the TCGA database." (PMID 34059057, 2021). "For example, the acetylation of lysine residues 45 and 46 in MPC1, or of lysines 19 and 26 in MPC2, was associated with reduced MPC activity in cancer and in the diabetic heart, respectively." (PMID 33804985, 2021). "We utilized online databases and uncovered that MPC1 expression is lower in many cancer tissues than in adjacent normal tissues." (PMID 34059057, 2021). "MPC1 is a novel cancer biomarker and potentially powerful therapeutic target for cancer diagnosis and treatment." (PMID 34059057, 2021).
cancer (continued). "Different authors now indicate that the repression or deletion of Mpc1 and Mpc2 is common in cancer, explaining the correlation between low MPC expression and poor survival seen in some cancers." (PMID 33804985, 2021). "Moreover, MPC1 deficiency may contribute to the growth, invasion, and metastasis of cancer cells." (PMID 34059057, 2021). "Decreased MPC1 expression promotes β-catenin nuclear transcription, enhances the Wnt/β-catenin pathway, and facilitates the expression of the cancer metastasis-related proteins MMP7, E-cadherin, Snail, and MYC, thus promoting CRC liver metastasis." (PMID 34059057, 2021). "While downregulation of the MPC1 expression seems to be detrimental for several forms of cancer, NASH/NAFLD phenotypes seem to benefit by the MPC disruption." (PMID 34025683, 2021). "The most well-known phenomenon associated with metastasis of cancer cells is EMT, which is strongly linked to the function of MPC1." (PMID 32708919, 2020). "The tendency for MPC1 expression in carcinomas to be lower in comparison to normal cells promotes EMT through glutamine metabolism." (PMID 30801869, 2019). "After performed successfully MPC1 knockout, the cells were extensive studied in consideration of migration, therapeutic sensitivities and the expression of cancer stem cell markers." (PMID 28624784, 2017). "Uptake of pyruvate by colonocyte mitochondria also decreases due to a deletion of the mitochondrial pyruvate carrier 1 (Mpc1) gene, an outcome that is observed among several cancers." (PMID 29231905, 2017). "Experiments with zebrafish – a model animal that is now commonly used in the field of cancer biology – showed that APC acts via mpc1 to regulate how the cell uses energy." (PMID 28397687, 2017). "Recent work has revealed that MPC1 is downregulated in various human cancers and that this correlates with poor survival." (PMID 28397687, 2017). "Reduced expression of MPC1 disrupts the transporter function, induces metabolic shift to increase glycolysis, and thus plays important roles in several diseases, including cancer." (PMID 26895100, 2016). "MPCs (particularly MPC1) were underexpressed in many cancers and low expression correlates with poor survival as reported by John C. Schell." (PMID 26413751, 2015). "Reduction in MPC1 levels and activity contribute to cancer progression by promoting epithelial to mesenchymal transition (EMT) or increasing resistance to chemotherapy, and lower MPC1 expression is associated with the PDAC glycolytic subtype, a marker of poor prognosis." (PMID 39363341, 2024). "Inhibition of Esrra has also been shown in cancer cell metabolism studies to interfere with pyruvate entry in mitochondria by inhibiting the expression of Mpc1, and inhibition of Esrra led to decreased expression of Ppargc1a-controlled expression of mitochondrial genes in mice brains." (PMID 39269443, 2024). "Several molecules regulate MPC1 to interfere with cancer cell proliferation." (PMID 36902385, 2023). "In fact, both of these transporters, particularly MPC1, are downregulated or absent in most cancer cells, and low MPC expression is associated with poor survival." (PMID 36902385, 2023). "Moreover, Mpc1/2 expression is of prognostic value in this cancer type: in a study of 88 patients, it correlated negatively with UICC stage and lymph node metastases, and positively with overall survival." (PMID 33804985, 2021). "We discuss the potential metabolism-altering effects of MPC1 in cancer, including decreased pyruvate transport ability; impaired pyruvate-driven oxidative phosphorylation (OXPHOS); and increased lactate production, glucose consumption, and glycolytic capacity, and the underlying mechanisms." (PMID 34059057, 2021). "The expression of MPC1, which encodes one subunit of mitochondrial pyruvate complex (MPC) that is responsible for transporting pyruvate into mitochondria, was downregulated in HGLO group in 15 cancer types." (PMID 34030708, 2021).